TAF9B (TATA-box binding protein associated factor 9b)
Description:
Essential for cell viability. TAF9 and TAF9B are involved in transcriptional activation as well as repression of distinct but overlapping sets of genes. May have a role in gene regulation associated with apoptosis. TAFs are components of the transcription factor IID (TFIID) complex, the TBP-free TAFII complex (TFTC), the PCAF histone acetylase complex and the STAGA transcription coactivator-HAT complex. TFIID or TFTC are essential for the regulation of RNA polymerase II-mediated transcription.
Synonyms: DN-7; TAF9L; TAFII31L; DN7; TFIID-31
Tractability: PROTAC: ubiquitination databases record sites on it; its protein half-life has been measured.
Gene: Protein-coding gene on chromosome X (78,129,748 to 78,139,688, reverse strand). Ensembl gene ENSG00000187325.
Subcellular location: Nucleus
Subcellular location (Human Protein Atlas): Nucleoplasm
Pathways (Reactome):
Gene expression (Transcription): RNA Polymerase II Pre-transcription Events; RNA Polymerase II Promoter Escape; RNA Polymerase II Transcription Initiation; RNA Polymerase II Transcription Initiation And Promoter Clearance; RNA Polymerase II Transcription Pre-Initiation And Promoter Opening
Disease: HIV Transcription Initiation; RNA Polymerase II HIV Promoter Escape; Transcription of the HIV genome
Metabolism of proteins: Ub-specific processing proteases
Gene Ontology:
Molecular function: protein binding; RNA polymerase II general transcription initiation factor activity; transcription corepressor activity; protein heterodimerization activity
Biological process: negative regulation of apoptotic process; negative regulation of transcription by RNA polymerase II; positive regulation of cell growth; protein stabilization; DNA-templated transcription initiation; transcription by RNA polymerase II
Cellular component: transcription factor TFIID complex; transcription factor TFTC complex; nucleoplasm; nucleus
Homologues: Orthologues: chimpanzee TAF9B (99% identical), macaque TAF9B (99% identical), pig TAF9B (96% identical), guinea pig TAF9B (95% identical), dog TAF9B (95% identical), rabbit TAF9B (95% identical), mouse Taf9b (90% identical), rat Taf9b (90% identical), Drosophila melanogaster Taf9 (38% identical), Caenorhabditis elegans taf-9 (22% identical). Paralogues in human: TAF9 (82% identical).
Diseases named in the same sentence as TAF9B in open-access papers:
TAF9B is named in the same sentence as 7 diseases in open-access papers, as found by Europe PMC text mining. Sharing a sentence is not in itself a finding about the gene and the disease. The quoted sentences say what the papers report.
breast carcinoma (1 paper, 2019). "In a recent study, among others, loss of heterozygosity of TAF9B has been identified to be associated with metastasis-free survival in breast cancer patients, indicating its potential value as prognostic marker." (PMID 31357971, 2019).
cataract (1 paper, 2014). Partial or complete opacity of the crystalline lens of one or both eyes that decreases visual acuity and eventually results in blindness. "Interestingly, we observed that Taf9b KO mice display defects in eye development including microphthalmia and cataracts-like phenotypes albeit with modest penetrance (data not shown)." (PMID 25006164, 2014).
TAF9B also shares sentences with these, for which no sentence is quoted: cancer (3 papers); tumor (2); astrocytomas (1); endometrial cancer (1); microphthalmia (1).